CD14 (CD14 molecule)
Diseases named in the same sentence as CD14 in open-access papers (continued):
Sharing a sentence is not in itself a finding about the gene and the disease.
glioblastoma (23 papers, 2012 to 2025). The most malignant astrocytic tumor (WHO grade IV). "We have previously shown that for glioblastoma and renal cell carcinoma patients, an increase in peripheral blood CD14+HLA-DRlo/neg monocytes was associated with increased infiltration of CD14+ cells within the tumor." (PMID 26286851, 2015). "In the last decade, CD14+HLA-DRlow monocytes were found in the blood of patients with B-cell lymphomas and glioblastoma, renal, and prostate cancers." (PMID 35237501, 2021). "Accordingly, we have previously shown that exosomes derived from the plasma of glioblastoma patients were able to reduce the proliferation of T lymphocyte and that this effect was mediated by CD14 + monocytes." (PMID 32332763, 2020). "We showed that CD14 and CD11b stained the same macrophage population residing in the glioblastoma tissue." (PMID 33348707, 2020). "Compared with CD14+ circulating blood cells of glioblastoma patients, blood coagulation function was more activated in glioblastoma-infiltrating CD14+ cells." (PMID 32396873, 2020). "In this study we describe the generation of DC from 31 Glioblastoma (GB) patients starting from their monocytes isolated by immunomagnetic CD14 selection using the CliniMACS® device." (PMID 23284979, 2012). "EVs from patients suffering from glioblastoma (GBM) are capable to polarize CD14+ and CD163+ monocytes toward the M2 anti-inflammatory phenotype, enhancing blood serum concentrations of colony-stimulating factor 2 and 3, as well as to detect interleukin-2, -4, and -13." (PMID 37511010, 2023). "Tissue sections from resected low-grade, meningioma, and glioblastoma (grade IV) tumors and epilepsy tissues were immunofluorescently triple-labeled for Iba1 (pan-myeloid marker), CD14 or CD163 (preferential TAM markers), and either P2RY12 or TMEM119 (microglial-specific markers)." (PMID 34286275, 2021). "Given the redundancy of representation of the miR-181 family by target prediction programs and genome wide profiling data, we evaluated the expression of each miR-181 family member in matched blood and glioblastoma tissue in the CD14+ blood monocyte and CD11b+ tissue macrophage population." (PMID 33348707, 2020). "Astrocyte subpopulation B (combined from all three brain regions) is mostly correlated with the mesenchymal glioblastoma gene signature, as the enriched genes in this gene set (e.g., Scpcp1, Rac2, Blcrb, Mrc2, Cd14, and C5ar, among others) are upregulated in this subpopulation." (PMID 30957015, 2019). "RNA interference of both β-catenin and CCL2 in GBM cells reduced migration of CD14+-monocytes towards TCM of glioblastoma cells." (PMID 35562953, 2022). "A decrease in CD11c+ CD14+ CD16+ HLA-DR high monocytes, accompanied by a significant increase in overall OS, was observed in recurrent glioblastoma after post-surgical Pembrolizumab, but only in patients that had also received neoadjuvant anti-PD-1 immunotherapy before surgery." (PMID 35625643, 2022). "Collectively, these data suggest that in the context of glioblastoma, CD14 and CD163 are not strictly TAM-specific markers and can be expressed by both myeloid cell populations, likely dependent on activation state." (PMID 34286275, 2021). "In addition, according to the database of the Ivy Glioblastoma Atlas Project, the distribution of PD-L1 was consistent with the distribution of the myeloid gene markers such as ITGAM, CD14, and CD68." (PMID 30333036, 2018). "Interestingly, glioblastoma-derived EVs drive the formation of non-classical monocytes (NCMs), CD14+/PD-1+/CD16+/HLA-DRhigh, a specific immunosuppressive cell population widely described as anti-inflammatory." (PMID 32225076, 2020). "Increased numbers of CD14+ HLA-DRlo/neg monocytes in the peripheral blood of OS patients has previously been shown to be immunosuppressive in a variety of cancers such as prostate cancer, non-Hodgkin lymphoma (NHL), glioblastoma multiforme, and chronic lymphocytic leukemia." (PMID 26286851, 2015).
malaria (23 papers, 2009 to 2024). Malaria is a serious and sometimes fatal disease caused by a parasite that commonly infects a certain type of mosquito which feeds on humans. "To the best of our knowledge, we have not found any other report that has examined association of this CD14 locus (rs2569190) in malaria and schistosomiasis co-infected individuals." (PMID 37684680, 2023). "Genotype and allele frequencies of the TLRs and CD14 polymorphisms in patients with Pv-malaria and healthy controls." (PMID 28850598, 2017). "Furthermore, we carried out a binary logistic regression model using schistosomiasis-malaria co-infection as outcome variable, and CD14 genetic variants as independent variable, while controlling for age, sex and PCV." (PMID 37684680, 2023). "Association of parasitemia with TLR and CD14 polymorphisms in Pv-malaria patients." (PMID 28850598, 2017). "However, CD14 gene polymorphisms are only one component of the complex host–parasite interaction, and thus constitute only a piece of the genetic puzzle required for a complete picture of the immune response to malaria." (PMID 31979279, 2020). "In the latest study on human infection with malaria parasites (Plasmodium falciparum and Plasmodium vivax), it was again confirmed that the absolute number of G-MDSCs (SCChiCD15+CD66b+CD11b+CD14-) increase in peripheral blood." (PMID 39212529, 2024). "The effect of Pf-EV stimulation on M1/M2 monocyte polarization revealed a more pronounced effect on CD14+CD16+ intermediate monocytes than the CD14+CD16− classical monocytes with a marked induction of Pf-EVs from a severe malaria strain." (PMID 36768950, 2023). "Since HLA-DR has been shown to reliably identify monocytes along with CD14, we later distinguished monocytes based on CD14 and HLA-DR co-expression for the two malaria vaccine groups." (PMID 33732548, 2021). "In more recent studies of children in malaria endemic Papua, New Guinea, γδ T cells and CD14+ monocytes are the primary cellular sources of cytokines and chemokines associated with severe malaria." (PMID 31900030, 2020). "Studies in malaria patients identified monocytes, particularly CD14+CD16+ inflammatory monocytes, and γδ T cells, as the main cellular sources of TNF." (PMID 30239833, 2019). "Other cellular proteins correlating with PF3D7_1460800 included alpha-1-B glycoprotein (A1BG), complement factor B (CFB), and CD14, which were previously reported to be differentially expressed in malaria patients." (PMID 29425228, 2018). "Partial inhibition was observed when H2DCFDA+CD14+CD16+ cells from malaria patients were cultured with Pv-Ret and assessed by flow cytometry." (PMID 25233271, 2014). "Three different MO subsets were identified in patients with acute uncomplicated malaria by CD14 and CD16 expression levels." (PMID 19851453, 2009). "Moreover, peripheral blood CD14+ monocytes, in patients with symptomatic malaria, were identified as the main leucocytic sources of CXCL10." (PMID 38541021, 2024). "Indeed, either blockade of mitochondrial complex I or blockage of NADPH oxidases, both responsible for ROS generation, efficiently reduces ROS levels in PBMC and CD14+CD16+ monocytes from malaria patients." (PMID 25233271, 2014). "Importantly, we demonstrate for the first time that CD14+CD16+ monocytes in malaria patients exhibited greater phagocytic activity and produced higher levels of intracellular TNF-α and reactive oxygen species, indicating their important role in parasite control and host resistance to infection." (PMID 25233271, 2014). "Hence, our results support the hypothesis that CD14+CD16+ monocytes display effector functions involved in parasite control during malaria." (PMID 25233271, 2014). "For example, leukocyte migration and chemotaxis, inflammatory and defence response, and cytokine production were enriched at day 0 during malaria in CD16+ monocytes and cDCs but enriched at day 28 in CD14+ monocytes." (PMID 37968278, 2023).
malaria (continued). "COMPLEMENT RECEPTOR 1 (CR1), a membrane immune adherence receptor that plays a critical role in the capture and clearance of complement-opsonized pathogens, was upregulated on both CD14+ and CD16+ monocytes and cDCs during malaria." (PMID 37968278, 2023). "Patients with severe and mild malaria also showed increased surface expression of TLR2 and TLR4 on CD14+ monocytes and cDCs and decreased intracellular expression of TLR9 on pDCs." (PMID 27716849, 2016). "Similar to mice, we observed a significantly increased frequency of circulating CD14+CD16−Caspase-1+ and CD14dimCD16+Caspase-1+ monocytes in peripheral blood mononuclear cells from febrile malaria patients." (PMID 24453977, 2014). "Together these data indicate that CD14+CD16− and CD14+CD16+ monocytes have a more activated and inflammatory profile than patrolling monocytes during malaria." (PMID 25233271, 2014). "Two major monocyte subpopulations have been described; one classical (CD14+CD16−) and one inflammatory (CD14+CD16+); the latter has been found to be increased during acute uncomplicated malaria." (PMID 21483827, 2011). "Adults with severe and mild malaria had increased expression of TLR2 and TLR4 on CD14+ monocytes and myeloid DCs and decreased expression of TLR9 on plasmacytoid DCs compared to adults with no history of malaria exposure." (PMID 19691558, 2009). "Using anti-CD14 and anti-CD16 it was possible to identify Hz-containing monocytes and granulocytes in whole blood from healthy human volunteers incubated with Hz as well as in a sample from a patient with malaria." (PMID 21453521, 2011).
mastitis (23 papers, 2008 to 2025). Inflammation of breast tissue during lactation or postpartum due to an obstructed duct or infection. "1,25(OH)2D3 induces localized expression of NOS2 in milk CD14+ cells and increased CCL5 in CD14- cells during experimentally induced mastitis caused by S. uberis." (PMID 36144467, 2022). "The significant changes in expression of LBP, TLR, CH3L1 and CD14 during the early stages of infection make them suitable candidates for early infection diagnostic biomarkers for sub-clinical mastitis." (PMID 32518370, 2020). "Published reports have revealed the importance of CD14 polymorphisms as candidates for studying diseases such as bovine tuberculosis and mastitis." (PMID 31963925, 2020). "The present study was undertaken with the objectives to characterize and to analyze combined genotypes of cluster of differentiation 14 (CD14) gene to explore its association with clinical mastitis in Karan Fries (KF) cows maintained in the National Dairy Research Institute herd, Karnal." (PMID 27536026, 2016). "However, it is also likely that over-stimulation of this pathway in CD14+ mammary epithelial cells would lead to serious inflammation and would therefore be the cause of mastitis." (PMID 19063729, 2008). "Immunity-related genes were also identified in the present study; for example, the CD14 gene was found in the NGI population and is linked to innate immunity, providing defense against pathogens responsible for mastitis and glomerulonephritis." (PMID 39729174, 2024). "The differences in the expression levels of MHCII and CD14 on milk macrophages indicate a significant modulatory effect of subclinical mastitis on the functional type of macrophages." (PMID 35498755, 2022). "The protective effect of recombinant bovine CD14 against infection by E. coli was demonstrated in a mouse mastitis model." (PMID 30142177, 2018). "The model presented here demonstrates that changes in the numbers of CD14− monocytes and CD14+ monocytes in the periphery prepartum predict the development of postpartum disease (mastitis, metritis)." (PMID 28222802, 2017). "Changes in the numbers of CD14− monocytes and CD14+ monocytes in the periphery predict the development of postpartum disease (mastitis, metritis)." (PMID 28222802, 2017). "Further research will be needed to conclude the relationships among CD14 genotypes, combined genotypes, concentration of CD14 in mammary tissues, and clinical mastitis." (PMID 27536026, 2016). "Gene insert containing the resistant variety of CD14 gene of CB cattle can be used for somatic gene therapy, particularly against mastitis." (PMID 22132326, 2011). "Additionally, a Streptococcus uberis (S. uberis) bovine mastitis model observed localized expression increased for CYP27B1 in milk CD14+ cells during active mastitis, while CD14- cells saw increased CYP24A1." (PMID 36144467, 2022). "Here, we report NGS approach coupled with advanced network and pathway biology methods to simultaneously profile the mRNA and miRNA networks that are differentially regulated in vivo in blood-isolated and milk-isolated CD14+ monocytes during infection with a bovine mastitis pathogen, S. uberis." (PMID 24470219, 2014). "Nonetheless, our observation is in agreement with another study which investigated the levels of CD14 in S. aureus or S. uberis bovine mastitic milk postpartum and concluded that low levels of CD14-positive cells might be an indicator of mastitis following calving." (PMID 29283389, 2017). "LPS was found to cause inflammation in mouse mammary glands by upregulating mRNA expression of the CD14/TLR4/NF-κB/MAPK pathway, while dexamethasone and ATF reduced LPS-induced mastitis in mice by downregulating mRNA expression of this pathway." (PMID 36090098, 2022). "On the contrary, CD14, TNF-α, MD-2, IL-1β, NF-kB, and IL-12 expression levels were decreased in mastitis tissue with respect to normal tissue." (PMID 25706977, 2015).
mastitis (continued). "In the present study, CD14, TNF-α, MD-2, IL-1β, NF-κB, and IL-12 gene expression was decreased in tissue affected by mastitis compared to normal mammary tissue, which is consistent with suppression of NF-κB activity and pro-inflammatory cytokine production." (PMID 25706977, 2015). "Statistical analysis of transcript and protein level expression changes indicated that 10 genes, namely TLR4, MyD88, IL-6, and IL-10, were up-regulated, while, CD14, TNF-α, MD-2, IL-β, NF-κB, and IL-12 were significantly down-regulated in mastitis tissue in comparison with normal tissue." (PMID 25706977, 2015). "Moreover, in some Gram-negative bacterial infections of mastitis, bacterial lipopolysaccharides (LPSs) can directly interact with neutrophils through CD14 expressed on the cell surface." (PMID 40005880, 2025).
colorectal cancer (21 papers, 2012 to 2025). A primary or metastatic malignant neoplasm that affects the colon or rectum. "There is a favourable correlation between the proportion of APOE+CTSZ+CD14+ cells and regulatory T cells in colorectal cancer samples." (PMID 39187937, 2024). "For instance, a large-scale analysis of transcriptome and microarray data demonstrated the correlation between high CD14 expression and poor survival outcomes in colorectal cancer patients." (PMID 39684692, 2024). "In KEGG pathway enrichment of abnormally methylated DEGs in CD14+ monocytes, colorectal cancer and Influenza A signaling pathways were significantly enriched in RA and SLE, respectively." (PMID 34079550, 2021). "MafB in CD14+ monocytes promoted tumorigenesis, cellular proliferation, and invasion in colorectal cancer, T cell acute lymphoblastic leukemia, nasopharyngeal carcinoma, and HCC." (PMID 31447817, 2019). "In a further experiment, we also enriched/cultured colorectal CTCs from another colorectal cancer patient, and demonstrated that the all of the cells also stained positively for the macrophage differentiation marker CD-14." (PMID 22829910, 2012). "Comparably, we found the intermediate CD14++CD16+ monocyte subset to be significantly elevated in colorectal cancer patients, but to show higher numbers in local than metastatic disease." (PMID 22973451, 2012). "Moreover, CD14 was also related to a broad range of ICIs, which implies its potential as a target molecule to enhance the immunotherapy of colorectal cancers." (PMID 39684692, 2024). "Thus, the invasive margin of colorectal cancers are enriched in CD14+ HLA-DR − cells in close proximity to T cells." (PMID 34727230, 2022). "Furthermore, an increase in the frequency of CD14 + CD169 + macrophages is associated with the development and progression of colorectal cancer and a higher level of both macrophages’ phenotypes (TAMs and M1)." (PMID 36498469, 2022). "High expression of B7-1 and B7-2 may indirectly affect the lymph node metastasis of colorectal cancer by influencing the expression of CD14 + macrophages." (PMID 36311731, 2022). "The observed IL-11 expression and STAT3 activation in CD11b+ and/or CD14+ cell-infiltrating tumour sites of colorectal cancer patients strongly suggests that the induction of MDSCs may be mediated by IL-11-STAT3 signalling in the tumour microenvironment." (PMID 28781374, 2015). "Furthermore, we confirmed that CD11b+ and/or CD14+ cells infiltrated in the same region of tumour tissues of colorectal cancer patients." (PMID 28781374, 2015). "In colorectal cancer, tumor-enriched FCN1+ monocyte-like cells exhibited a high resemblance to blood CD14+ monocytes, likely representing a monocyte population that migrates into tumors and adopts a tumor-specific transcriptional program." (PMID 40367012, 2025). "Furthermore, a significant abundance of APOE+CTSZ+CD14+ cells, which exhibit immunosuppressive properties by increasing the expression of anti‐inflammatory genes, has been detected in a substantial number of tumour specimens, specifically in cases of colorectal cancer." (PMID 39187937, 2024). "Evidence was provided that in human colorectal cancer, NADPH oxidase components p47phox and p67phox and the myeloid marker CD14 correlate with IL-23p19 expression levels." (PMID 28191009, 2017). "Univariate analysis revealed age, plasma, VEGF-A and the blood levels of CD14++CD16+ intermediate monocytes (p = 0.004, odds ratio = 22) as predictors for colorectal cancer." (PMID 22973451, 2012). "The effect of inhibiting arginase 1 (ARG1) and nitric oxide synthase 2 was assessed using the small molecule inhibitors NOHA and L-NMMA, respectively, and was found not to rescue T cell proliferation inhibited by colorectal cancer patient’s CD14 + cells." (PMID 34727230, 2022). "Dissociation of human colorectal cancers revealed a significant increase in the frequency of CD14+ cells in the tumour compared to matched non-cancerous tissue (p = 0.005)." (PMID 34727230, 2022).
colorectal cancer (continued). "Within colorectal cancer, small proportions of blood-derived monocytes, including CD14+ classical, CD14+CD16+ intermediate, and CD16+ nonclassical subsets were observed." (PMID 34572013, 2021). "Circulating MDSCs from colorectal cancer patients express high CD13, low CD115, CD117 and CD124 (IL-4Ra) and negative CD14, CD15, CD66b and CD34." (PMID 23437326, 2013).